BECN1 (beclin 1)
Diseases named in the same sentence as BECN1 in open-access papers (continued):
Sharing a sentence is not in itself a finding about the gene and the disease.
lung carcinoma (101 papers, 2012 to 2025). "It has also been demonstrated that BECN1 deficient mice are more susceptible to develop hepatocellular and lung carcinomas as well as lymphomas." (PMID 40248706, 2025). "Research showed that reducing miR-30a-5p levels in lung cancer can increase Beclin-1 expression, causing drug resistance." (PMID 39650649, 2024). "On the other hand, VPS34 depletion in lung cancer cells was found to not only impair the activity of NEDD4-1 to stabilize Beclin-1, but also cause NEDD4-1-mediated proteasomal degradation of Beclin-1 via K11-linked ubiquitination." (PMID 36918822, 2023). "Biallelic loss of Becn1 is embryonically lethal for knockout mice, and promotes spontaneous tumorigenesis of lymphomas, liver and lung cancers." (PMID 33425768, 2020). "In a study on lung cancer cells, miR-17-5p downregulation was associated with an increased expression of beclin 1 gene, which is an autophagy modulator in the survival pathway." (PMID 31252688, 2019). "Bi-allelic loss of Beclin 1 in mice is embryonically lethal and mice with mono-allelic loss of Beclin 1 have an increased incidence of spontaneous tumorigenesis, including lymphomas, liver and lung cancers." (PMID 25196438, 2014). "All these data collectively proved that overexpression of miR-17-5p into paclitaxel resistant lung cancer cells caused reduction in cellular autophagy by directly targeting autophagy related protein BECN1." (PMID 24755562, 2014). "However, autophagy inhibition following Beclin 1 knockdown can cause various types of cancers (such as lymphoma, liver cancer, and lung cancer)." (PMID 36310624, 2022). "Importantly, a positive association was observed between PANDAR and BECN1 in lung cancer tissues (r = 0.789, P < 0.001)." (PMID 32626525, 2020). "Our results indicated that paclitaxel resistance of lung cancer is associated with downregulation of miR-17-5p expression which might cause upregulation of BECN1 expression." (PMID 24755562, 2014). "In this regard, by increasing caspase activity and decreasing cell survival, the suppression of autophagy by Atg5 and Beclin-1 siRNA improves cisplatin sensitivity in lung cancer cells." (PMID 40248706, 2025). "Gedunin has been demonstrated to disrupt the interaction between Hsp90 and key proteins, including Beclin-1 and Bcl-2, thereby inducing increased apoptosis in A549 lung cancer cells." (PMID 40357400, 2025). "Previous studies have shown that BECN1‐mediated autophagy is associated with leukemia resistance to CTX; lung cancer, embryonal carcinoma, cervical carcinoma resistance to DDP; and cervical cancer resistance to VP16." (PMID 39411839, 2024). "In lung cancer, for example, the enhanced expression of Beclin-1 overcomes radiation resistance, and the induction of autophagy sensitizes NSCLC and glioblastoma cells to radiation." (PMID 39335139, 2024). "Cisplatin enhances autophagy and apoptosis in A549 human lung cancer cells by increasing Beclin 1 and Atg5, while blocking these autophagy-related proteins worsens apoptotic cell death." (PMID 39650649, 2024). "On the other hand, studies in lung cancer, human synovial sarcoma cells, and leukemia cells have shown that overexpression of Beclin 1 promotes cell death." (PMID 37004094, 2023). "A recent study found that USP14 stabilized Beclin 1 to reduce autophagy-dependent ferroptosis induced by 6-Gingerol in lung cancer cells." (PMID 36596780, 2023). "In particular, down-regulation of BECN1 has been reported in lymphoma, melanoma, osteosarcoma and brain and lung cancers." (PMID 37887330, 2023). "TNF receptor-associated factor 6 (TRAF6)-BECN1 signaling axis plays a pivotal role in autophagy induction through ubiquitination of BECN1, thereby inducing lung cancer migration and invasion in response to toll-like receptor 4 (TLR4) stimulation." (PMID 35422093, 2022).
lung carcinoma (continued). "The downregulation of NDC80 inhibited the formation of autophagosomes, and reduced the expression of autophagy-related proteins such as LC3II, Beclin-1, and p62 in lung cancer cells." (PMID 36105209, 2022). "Beclin-1 has been reported to be targeted by miR-30a in liver cancer cells and by miR-216b in lung cancer cells, and both miRs are downregulated in both cancer types, suggesting their role in autophagy activity." (PMID 35444536, 2022). "In this way, enhanced ATG7 levels promote the conversion of LC3-I into LC3-II and improve Beclin-1 expression, supporting autophagy and chemoresistance of lung cancer (Huang FX." (PMID 35444536, 2022). "Meanwhile, a previous study also suggested that lung cancer cells diminished the miR-216b levels to induce the production of autophagy protein Beclin-1 to augment cell survival, which is in accordance with our findings." (PMID 34345220, 2021). "Numerous studies have indicated that BECN1 is not only involved in the formation of autophagosome, but also influences the development of lung cancer by regulating cell autophagy levels." (PMID 32626525, 2020). "In conclusion, this study has confirmed that lncRNA PANDAR can affect the development of lung cancer by regulating the expression of BECN1 gene." (PMID 32626525, 2020). "Materials and Methods: The expression profile and clinical application of PANDAR and its possible target gene BECN1 were tested in 276 cases of lung cancer tissues." (PMID 32626525, 2020). "In this research, we investigated the expression profile and clinical application of lncRNA PANDAR and possible target gene BECN1 in lung cancer tissues." (PMID 32626525, 2020). "The dimer formed by phosphorylated STAT3 (Y-705) goes into the nucleus, directly binds to the promoter region of BECN1 and represses its transcription in lung cancer cells." (PMID 28526807, 2017). "In human lung cancer lesions, expression of ER stress proteins is linked to autophagy-related proteins such as LC3 and Beclin-1." (PMID 27588471, 2016). "Here in this report, we demonstrated that miR-17-5p mediated regulation of autophagy by targeting BECN1 contributed to paclitaxel resistance in two lung cancer cell lines, A549 and H596 cells." (PMID 24755562, 2014). "Our results clearly indicated that inhibition of beclin-1 mediated autophagy by miR-17-5p overexpression significantly sensitized the paclitaxel resistant lung cancer cells to paclitaxel." (PMID 24755562, 2014). "Decreased Beclin 1 mRNA expression has been observed in glioblastoma, high-grade brain tumors and lung cancer." (PMID 25196438, 2014). "All these data collectively demonstrated that overexpression of miR-17-5p resulted in inhibition of autophagy in paclitaxel-resistant lung cancer cells by targeting BECN1." (PMID 24755562, 2014). "Knockdown of Beclin 1 in mice leads to inhibition of autophagy and subsequently a high incidence of spontaneous tumors, including lymphoma, liver and lung cancer." (PMID 24260370, 2013). "For instance, in several cancers, Beclin-1 has been shown to suppress tumor growth in some malignancies, such as lung cancer, synovial sarcoma, and laryngeal squamous carcinoma, while promoting tumor progression in others, such as colon cancer and ER-positive breast cancer." (PMID 40894905, 2025). "In addition to its role in inhibiting cancer cell metastasis, miR-30a has recently received attention for its potential to sensitize drug-resistant lung cancer cells by impeding beclin 1-executed autophagy." (PMID 38339408, 2024).
lung carcinoma (continued). "In addition, it has been described that the inhibition of this miRNA promotes chemoresistance in lung cancer by directly regulating the expression of BECN1." (PMID 39057123, 2024). "In another study, bis-indole derivatives of 1-methoxyspirobrassinol methyl ether induced autophagy in A549 (lung carcinoma epithelial cells) by modulation of the phosphorylation or expression of various autophagy markers, such as Beclin-1, AMPK, ULK1, p62, Atg7, and LC3A/B." (PMID 38675591, 2024). "Other studies also demonstrated that HIF-1α-induced autophagy could contribute to the cisplatin resistance of ovarian and lung cancer cells via the upregulation of Beclin-1 and LC3." (PMID 36551540, 2022). "Consistently, BECN1 has been reported as an oncogene in non-small-cell lung cancer, which could enhance paclitaxel resistance through involvement in autophagy in lung cancer cells." (PMID 35012553, 2022). "The prognostic role of Beclin 1 in lung cancer is still controversial." (PMID 36401689, 2022). "Similarly, the suppression of AKT, increase in beclin-1, and subsequent induction of autophagy in lung carcinoma cells treated with amino-GQD were accompanied by activation of p38 MAPK, while no increase in ERK or JNK phosphorylation was observed." (PMID 34439299, 2021). "PANDAR by upregulation of BECN1 expression via activating autophagy and apoptosis pathways could inhibit the development of lung cancer." (PMID 34367998, 2021). "Therefore, we deduced lncRNA PANDAR should be associated with BECN1, and PANDAR involved in the development of lung cancer by regulating autophagy pathway in lung cancer." (PMID 32626525, 2020). "As to the role of autophagy in lung cancer, haploinsufficiency of a key autophagy mediator, Beclin1, in genetically modified mice resulted in the formation of lung adenocarcinomas, and the Beclin-1 expression level was positively correlated with overall survival of patients with NSCLCs9,10." (PMID 31308361, 2019). "In this study, we revealed that autophagy inhibition using autophagy specific inhibitors (CQ and 3MA) and silencing autophagy-related gene (beclin-1) could significantly sensitize lung cancer cells to anlotinib cytotoxicity in vitro in a synergistic manner." (PMID 30755242, 2019). "Beclin-1 is deleted in 40- 75% of cases of humansporadic breast, ovarian, and prostate cancers.Knocking down ATG5 and beclin-1, two knownessential autophagic molecules, can cause radiationresistance among lung cancer cells." (PMID 25780525, 2015). "Based on the molecular mechanism by which USP15 is negatively implicated in the autophagy induction through deubiquitination of BECN1, our study suggests that the negative regulation of USP15 in lung cancer progression might be functionally implicated in the regulation of autophagy induction." (PMID 35422093, 2022). "Importantly, recent studies have reported that autophagy facilitates TLR-induced migration and invasion of lung cancer cells through the TRAF6-induced ubiquitination of BECN1, suggesting that TLR-induced autophagy is functionally associated with lung cancer progression." (PMID 35422093, 2022). "Moreover, lung cancer patients with either high USP5 or Beclin 1 protein levels had a worse OS." (PMID 36528652, 2022). "For example, some studies demonstrated that targeting autophagy may be used in the future for the treatment of lung cancer because the disruption of autophagy via the inhibition of Atg5 and Beclin 1 may promote cisplatin-induced apoptotic cell death in A549 human lung cancer cells." (PMID 32802131, 2020). "However, in lung cancer cells, the inhibition of Beclin 1 lead to radiation resistance, and overexpression of Beclin 1 could enhance radiation sensitivity of cancer cells." (PMID 28881721, 2017). "IL-7 was discovered to lower Beclin-1 levels and activate the PI3 K/Akt/mTOR pathway in lung cancer cells." (PMID 39650649, 2024).
lung carcinoma (continued). "In a model of lung cancer, knockdown of ATG5, BECN1, ATG7 and p62/SQSTM1 decreases A549 cell invasiveness in the presence of cancer-associated fibroblasts (CAFs)." (PMID 37887330, 2023). "Conversely, CHIL31 depletion decreased the conversion from LC3-I to LC3-II in lung cancer cell lines as well as the expression of GABARAPL1, ATG5, p62, and Beclin-1." (PMID 37340009, 2023). "Cisplatin increased the protein levels of ATG5, Beclin-1, and LC3 in lung cancer cells, exhibiting features indicative of autophagy." (PMID 36551540, 2022). "Given the results that USP15 negatively regulated lung cancer migration and invasion through inhibition of autophagy induction by deubiquitination of BECN1, we tried to find the clinical relevance of USP15 in the regulation of lung cancer progression." (PMID 35422093, 2022). "Here, we observed that digitoxigenin and digoxin promote cell death of A549 lung cancer cells and have a pro-survival ATG5 and BECLIN-1-dependent autophagic activity in RNVCs." (PMID 35159285, 2022). "Thus, we screened DUBs for Beclin 1 that may have clear clinical relevance to lung cancer patients." (PMID 36528652, 2022). "Beclin 1 expression was reported negatively correlate with tumor grade, lymph node involvement, TNM stage, tumor size, dedifferentiation, and recurrence of lung cancer." (PMID 33425768, 2020). "While BECN1 was in a lower expression in lung cancer tissues than in normal lung tissues, there was a positive correlation relationship between PANDAR and BECN1." (PMID 32626525, 2020). "In this study, we analyzed the clinical influence of five autophagy-related genes including LC3A, LC3B, Beclin-1, Atg5, and p62 and investigated the epigenetic regulation of one of the autophagy genes LC3A in human lung cancer." (PMID 29545906, 2018). "Using TCGA database, we observed an inverse correlation between beclin-1 expression and MEK phosphorylation in lung cancer samples, which supported our preclinical data." (PMID 28558758, 2017). "On the other hand, miR-17 and miR-16 increased paclitaxel sensitivity of lung cancer cells through simultaneous downregulation of autophagy and activation of apoptosis following BECN1/Beclin 1 and BCL-2 suppression, respectively." (PMID 28459042, 2017). "Here, it was found that ING5 overexpression in vivo and vitro induced the autophagy of lung cancer cells with ATG13, ATG14 and Beclin-1 overexpression, indicating that ING5-induced autophagy was dependent on Beclin-1 and belonged to canonical pathway." (PMID 27409347, 2016). "To extend our finding we prepared another paclitaxel resistant lung cancer cell line H596-TxR from paclitaxel sensitive NCI- H596 cells in vitro and examined the status of BECN1 and LC3 in this resistant lung cancer cell line (H596-TxR)." (PMID 24755562, 2014). "mRNA and protein levels of Beclin-1 and LC3B are also significantly decreased in lung cancer tissues." (PMID 25202355, 2014). "Recently, decreased expression of Beclin 1 and LC3 were detected in human lung cancer tissues, indicating a possible role in the pathogenesis of lung cancer." (PMID 24260370, 2013). "The treatment of lung carcinoma, colon carcinoma, neuroblastoma, and monocyte/macrophage leukemia cells with GO or GQD nanoparticles increased the intracellular levels of beclin-1, a mammalian ortholog of ATG6 required for localization of autophagic proteins to a pre-autophagosomal structure." (PMID 34439299, 2021). "However, it should be noted that the cytotoxicity of amino- and hydroxy-GQD in lung carcinoma cells was increased by 3-methyladenine, which suppresses autophagosome formation by blocking class III PI3K and its subsequent interaction with beclin-1." (PMID 34439299, 2021).
lung carcinoma (continued). "Moreover, autophagy related gene BECN1 was also downregulated in lung cancer tissues comparison with normal tissues (P < 0.01), and there was a significant positive correlation between PANDAR and BECN1 levels (r = 0.789, P < 0.001)." (PMID 32626525, 2020). "To assess the impact of beclin-1 on MEK1 activation, we analyzed the correlation between beclin-1 expression and MEK1 phosphorylation in a cohort of lung cancer patients that had altered levels of beclin-1 protein expression as measured by reverse-phase protein array (RPPA)." (PMID 28558758, 2017). "Notably, ubiquitination levels of BECN1 and TRAF6 were remarkably enhanced in ARRB2KO lung cancer cells, strongly indicating that ARRB2 could inhibit the TRAF6-BECN1 signaling axis for autophagy induction." (PMID 37443143, 2023). "However, the alteration of the other autophagy-regulating proteins (Atg5, Atg12, and Beclin-1) was not significantly detected in human lung cancer cells cultured with 50 μM cisplatin compared to those non-treated control cells." (PMID 34321115, 2021). "Icotinib increased ATG3, ATG5, and ATG7 expression, but without affecting Beclin-1, VPS34 and ATBG14 levels in icotinib-resistant lung cancer cells." (PMID 35690866, 2022). "Similar results from previous studies have revealed that the expression of Beclin-1 and LC3B in lung cancer tissues was not affected by patient age, gender, smoking, histological type, lymph node metastasis or TNM stage." (PMID 25202355, 2014). "The significantly lower Beclin 1 mRNA expression seen in HCC by comparison with non-cancerous CH and CIRR tissues probably reflects previous observations in other types of human tumor, e.g. in ovarian, breast, prostate and lung cancer." (PMID 22928777, 2012).